TLR3 (toll like receptor 3)
Diseases named in the same sentence as TLR3 in open-access papers (continued):
Sharing a sentence is not in itself a finding about the gene and the disease.
breast carcinoma (continued). "The first report that TLR3 can directly trigger apoptosis in human breast cancer cells opened a new avenue for cancer therapeutics." (PMID 21861882, 2011). "TLR3 activation by its agonist directly triggers apoptosis in human breast cancer cells through activation of extrinsic caspases." (PMID 21861882, 2011). "The aim of this study was to investigate the expression and clinical relevance of TLR3, 4 and 9 in breast cancer." (PMID 21129170, 2010). "Synthetic dsRNA both induced apoptosis and blocked the proliferation of breast cancer cells in a TLR3 and TRIF-dependent manner." (PMID 19025601, 2008). "Additionally, TIR signaling contributes to CSC stemness maintenance; for example, TLR3 cooperates with β-catenin and NF-κB to promote the transformation of breast cancer cells into CSCs, directly leading to therapy resistance." (PMID 41488647, 2025). "Therefore, this study aimed to determine the anti-inflammatory effect of GEN on breast cancer cells due to the activation of the TLR3 signaling pathway via Poly I:C stimulation." (PMID 40844548, 2025). "Notably, TLR3 has also a critical role in immunogenic therapy-induced immune response in breast cancer patients." (PMID 41469691, 2025). "TLR3 activation in breast cancer cells can also promote tumor growth and metastasis by triggering inflammation, angiogenesis, and immune suppression through pathways such as NF-κB and MAPK, by promoting the expression of pro-inflammatory cytokines, angiogenic factors, and regulatory cytokines." (PMID 38903515, 2024). "TLR3 plays a multifaceted and intricate role in breast cancer pathogenesis." (PMID 38903515, 2024). "The stimulation of TLR3 by its agonist, dsRNA, prompts apoptosis in human breast cancer cells." (PMID 38903515, 2024). "TLR3 expression in DCs plays a crucial role in breast cancer." (PMID 38903515, 2024). "In breast cancer, TLR3 predominantly serves as a tumor-suppressive factor." (PMID 38903515, 2024). "Understanding how these pathways regulate these processes in the context of TLR3 activation could provide insights into the complex roles TLR3 plays in breast cancer progression and tumor microenvironment modulation." (PMID 38903515, 2024). "TLR3 regulates inflammatory factors in the breast cancer microenvironment." (PMID 37005579, 2023). "Recent studies have suggested that TLR3 has therapeutic potency in breast cancer." (PMID 37005579, 2023). "To further investigate the functions of TLR3 in breast cancer, we performed GSEA using TCGA data." (PMID 37005579, 2023). "Moreover, we performed immunohistochemical staining to analyze TLR3 expression in breast cancer tissue microarrays." (PMID 37005579, 2023). "Previous studies demonstrate that TLR3 is expressed in breast carcinoma and Kaposi’s sarcoma cells." (PMID 35737804, 2022). "In a randomized clinical trial, adjuvant treatment with poly(A:U) dsRNA was associated with a significant decrease in the risk of metastatic relapse in TLR3(+) breast cancer patients but not in TLR3(-) patients." (PMID 33986756, 2021). "Moreover, prognosis analysis indicated that breast cancer patients with high TLR3 levels had a poor overall survival (p=0.026)." (PMID 34531911, 2021). "TLR3 stimulation can also result in the induction of breast cancer stem cells (CSCs)." (PMID 33986756, 2021). "The TLR3 ligand, poly-AU, increases the survival rate in patients with TLR3-positive breast cancer." (PMID 33747948, 2021). "TLR3 stimulation by Poly I:C or BCG has been implicated in promoting tumor cell death in a multitude of cancers, including breast cancer, colon cancer, bladder cancer, head and neck carcinoma, pharynx carcinoma, hepatocellular carcinoma, lung cancer and melanoma." (PMID 33679703, 2020). "We found that human MCF-7 breast cancer cells express high basal levels of TLR3 and Wnt5a RNA." (PMID 29371911, 2017). "TLR3 activation mediated by dsRNA was shown to trigger apoptosis of human breast cancer cells." (PMID 27092172, 2016).
breast carcinoma (continued). "TLR3 was previously detected in papillary thyroid, lung, and breast cancer." (PMID 27191981, 2016). "To test this hypothesis, we evaluated the association of rs3775291 in TLR3 and rs4833095 in TLR1 with breast cancer survival in 715 primary breast cancer patients in a cohort of prospectively observed Chinese patients." (PMID 26226228, 2015). "Furthermore, TLR3 agonists have been shown to be safe and well tolerated in breast cancer settings." (PMID 40573960, 2025). "Notably, high expression of TLR3 in triple-negative breast cancer indicates a better prognosis, and TLR3-activated cDCs produce IFN- λ, which is linked to a good clinical outcome in breast cancer." (PMID 38903515, 2024). "TLR3 expression may be a potential prognostic molecular marker of poor survival in breast cancer." (PMID 37005579, 2023). "Furthermore, our study suggested that TLR3 is less frequently expressed in breast cancer tissues." (PMID 37005579, 2023). "In addition, the stable overexpression of TLR3 could inhibit cell proliferation in vitro and in vivo and correlate with less invasive phenotypes of breast cancer cells." (PMID 35748782, 2022). "Thus, TLR3 agonists may represent a suitable adjuvant for the design of DC vaccines against breast cancer." (PMID 35148751, 2022). "For example, high expression of TLR3 prolonged the survival time of patients with non-small-cell lung cancer by inducing apoptosis of cancer cells, but high expression of TLR3 could promote the migration of breast cancer cells by increasing the expression of E-cadherin." (PMID 36419829, 2022). "It has been demonstrated that stimulation of TLR3 drives breast cancer cells toward a cancer stem cell phenotype, which requires simultaneous activation of the β-catenin and NF-κB signaling pathway, implying a cooperative and synergistic function of β-catenin in TLR3-activated NF-κB signaling." (PMID 27713747, 2016). "However, TLR3 exhibited an antiproliferative role in human breast cancer and melanoma." (PMID 24932259, 2014). "In 2022, Yuan Chunhui and others constructed engineered exosomes-HELA-Exos, combining Toll-like receptor 3(TLR3) agonists and immunogenic cell death(ICD) inducers, which can activate dendritic cells in situ and specifically induce ICD in breast cancer cells." (PMID 39253075, 2024). "In this study, we evaluated the role of TLR3 in breast cancer using our original Fudan University Shanghai Cancer Center (FUSCC) datasets and breast cancer tissue microarrays." (PMID 37005579, 2023). "To identify signaling pathways that are differentially activated in breast cancer, we conducted gene set enrichment analysis (GSEA) between low– and high–TLR3 expression datasets." (PMID 37005579, 2023). "The TLR3 adjuvant, poly-ICLC, plus breast cancer vaccine have been found to provide modest immune stimulation." (PMID 37005579, 2023). "Herein, we developed and optimized a formulation of target-specific exosomes loaded with Hiltonol (TLR3 agonist) and the ICD inducer human neutrophil elastase (ELANE) to form an in situ DC vaccine for breast cancer treatment." (PMID 35148751, 2022). "TLR2, TLR3, and TLR4 as biomarkers of proinflammatory response were increased significantly in patients with inflammatory bowel disease and breast cancer." (PMID 35425840, 2022). "In similarity to TLR3, there are also some studies reporting the importance of TLR9 in the regulation of lipid peroxidation in patients with breast carcinoma." (PMID 33336901, 2021). "To establish interferon induction in breast cancer MDA-MB-231 cultured cells, we looked for interferon stimulated genes (ISG) including: OAS1, OAS3, RIG1, TLR3 and IFI16 genes." (PMID 32817625, 2020). "The status of TLR3 in cancer cells have been reported to predict favorable prognosis in neuroblastoma, HCC, NSCLC, and breast cancer." (PMID 33036630, 2020).
breast carcinoma (continued). "Based on our previous findings that C10 significantly reduced IL-6 protein levels and STAT3 phosphorylated via TLR3 signaling in other cancers, we also evaluated these in MCF-7 breast cancer cells." (PMID 29371911, 2017). "Our results demonstrate that C10 inhibits TLR3 and Wnt5a mRNA expression in MCF-7 breast cancer cells." (PMID 29371911, 2017). "Our study aimed to explore the possible effects of the SNPs rs3775291 in TLR3 and rs4833095 in TLR1 on the prognosis of breast cancer patients." (PMID 26226228, 2015). "In this prospective observational study, rs3775291 in TLR3 and rs4833095 in TLR1 were genotyped in 715 patients with primary breast cancer in a Chinese population." (PMID 26226228, 2015). "In this study, we found that TLR3 activation did induce certain tumor cell death while concurrently potentiating CSC phenotypes and tumor-initiating capacity in breast cancer cells." (PMID 25257174, 2015). "Cardamonin is capable of effectively abolishing TLR3 activation-enhanced CSC phenotypes in vitro and successfully controlling TLR3 stimulation-induced tumor growth in human breast cancer xenografts." (PMID 25257174, 2015). "Here, we investigated the association of two missense SNPs, rs3775291 (c.1234G>A) in the TLR3 gene and rs4833095 (c.743T>C) in the TLR1 gene, with relapse-free survival (RFS) in a cohort of prospectively observed breast cancer patients." (PMID 26226228, 2015). "TLR3-dependent IFN-β production induced by poly(I:C) inhibits growth of clear cell renal cell carcinoma and breast cancer cells." (PMID 23151919, 2012). "The purpose of the present study was to investigate the expression of TLR3, TLR4 and TLR9 in breast cancer as well as its relation to distant metastasis." (PMID 21129170, 2010). "Therefore, TLR3 may represent a good therapeutic target in breast cancer." (PMID 21129170, 2010). "The expression levels of TLR3, TLR4 and TLR9 have clinical interest as indicators of tumor aggressiveness in breast cancer." (PMID 21129170, 2010). "The expression levels of TLR3, TLR4 and TLR9 were analyzed on tumors from 74 patients with breast cancer." (PMID 21129170, 2010). "Consequently, TLR-3, TLR-6, TLR7/8, and TLR-9 agonists are considered among the most promising immunotherapeutic agents for breast cancer treatment." (PMID 41550509, 2026). "In studies on TLR-mediated enhancement of CSC stemness, in breast cancer, TLR3 activation drives the conversion of non-CSCs into CSCs by synergistically activating the β-catenin and NF-κB pathways, leading to tumor recurrence." (PMID 41488647, 2025). "However, the introduction of a MyD88 inhibitor disrupted the signal transduction of the TLR3-MyD88-NF-κB (p65)-IL6-Cyclin D1 pathway, leading to reduced breast cancer cell proliferation." (PMID 38347830, 2024). "In breast cancer, TLR3 could inhibit tumor proliferation by interacting with the GFR/PI3K/AKT pathway, suggesting that TLR3 is a potential repressor for breast cancer initiation and progression." (PMID 38738791, 2024). "The expression level and the positive rates of TLR3 were compared between breast cancer tissue and adjacent normal tissue samples by immunohistochemistry on microarray." (PMID 37005579, 2023). "Therefore, the combination of TLR3 agonists with ICD inducers based on cell-free exosomes offers a powerful and novel therapeutic platform for designing DC vaccines for breast cancer." (PMID 35148751, 2022). "However, the mRNAs of TLR3, Ifih1/MDA5, Zbp1, Ddx60 and Ifi204 were upregulated by varying degrees after poly(I:C) transfection in both mammary carcinoma and fibrosarcoma cells." (PMID 35737804, 2022). "(A) Allogenic breast cancer-derived exosomes isolated from MDA-MB-231 cells were genetically engineered to overexpress α-LA and simultaneously loaded with the ICD inducers ELANE and Hiltonol (TLR3 agonist) to generate HELA-Exos." (PMID 35148751, 2022).
breast carcinoma (continued). "We investigated the role of TLR3 signaling in the upregulation of HAO1 in alveolar epithelial cells and found that TLR3 signaling was required for HAO1 expression in alveolar epithelial cells induced by primary breast cancer." (PMID 35739335, 2022). "Hsp27 in the peripheral blood, through indirect interaction with toll-like receptor 3 (TLR3) and subsequent NF-κB activation, increased the secretion of vascular endothelial growth factor (VEGF) and activated VEGF receptor type 2 in breast cancer cells, ultimately promoting angiogenesis." (PMID 35453647, 2022). "Surprisingly, this effect was by no means correlated with TLR3 levels in CCA cells, although TLR3 expression is proposed as a biomarker for the therapeutic efficacy of dsRNA in breast cancer patients." (PMID 33036630, 2020). "Interestingly, type I interferon signaling downstream of toll-like receptor 3 (TLR3) signaling, is required for anthracycline-induced ICD in a murine breast cancer model." (PMID 31781488, 2019). "This trial sought to improve vaccine activity in breast cancer by the addition of a TLR3 agonist and the limitation to patients without high tumor burdens." (PMID 29157306, 2017). "Interestingly, the gene sets of ISs (AIM2, IFIH1 and TLR3), ISs and IFN-β (IFNB1), and all (ISs, IFNB1, IRF7 and TRAIL) showed strong correlations in ER-negative and lymph node positive or basal-like breast cancer patient survival." (PMID 27077807, 2016). "Similar findings were shown in 9-cis-retinoic-acid (9cRA) treatment of SK-BR-3 breast cancer cells, which revealed no significant change of TLR3, MDA5 and PKR, but significant up-regulation of RIG-I." (PMID 26208481, 2015). "Specifically, CD44 and ALDH1, two important breast CSC markers, increased 2- to 17-fold in all cell lines examined, suggesting that TLR3 activation, but not TLR5, 7, and 8, associates with CSC properties in different subtypes of breast cancer cells." (PMID 25257174, 2015). "Collectively, these data demonstrate that the NF-κB signaling pathway is not exclusively responsible for TLR3 activation-enhanced CSC phenotypes in breast cancer cells." (PMID 25257174, 2015). "Our results show high expression of TLR3, TLR4 and TLR9 by breast cancer cells though." (PMID 21129170, 2010). "Further mechanistic studies with BP nanoparticles revealed the activation of Toll-like receptor 3 (TLR3)-mediated innate-to-adaptive immune signaling as the mechanism of tumor growth and metastasis inhibition in multiple mouse breast cancer models, with no discernible toxicity observed in the mice." (PMID 41164345, 2025). "Moreover, the up‐regulation of TLR3, TLR4 and TLR9 expressions could increase the probability of biochemical recurrence and cancer metastasis in prostate and breast cancer, respectively." (PMID 33336901, 2021). "In addition to its effect on constitutive TLR3, Wnt5a levels and subsequent IL-6 production and STAT3 levels/activation, we then evaluated the ability of C10 to inhibit the migration and viability/growth of MCF-7 breast cancer cells." (PMID 29371911, 2017). "A triad of TLR3 stimulation, NF-κB and β-catenin activities in promoting CSC phenotypes indicates a combinational use of TLR3 agonists with NF-κB and β-catenin inhibitors, but neither alone, may help to improve clinic outcomes and efficacy of TLR3 agonists in patients with breast cancer." (PMID 25257174, 2015). "Moreover, TLR3 and TLR9 exhibited varying expression levels in estrogen receptors (ER-)/progesterone receptors (PR-) negative breast cancer when contrasted with control tissues." (PMID 41550509, 2026). "Due to a lack of TLR family immunohistochemical samples, only TLR3, TLR4, TLR7, and TLR8 staining results in colorectal cancer, breast cancer, prostate cancer, and normal tissue were exhibited, which were largely consistent with the previously reported mRNA expression." (PMID 35801728, 2022).
melanoma (87 papers, 2008 to 2025). A malignant, usually aggressive tumor composed of atypical, neoplastic melanocytes. "Increased TLR3 expression is associated with better survival outcomes in hepatocellular carcinoma, melanoma, non-small cell lung carcinoma (NSCLC), neuroblastoma, and colorectal carcinoma." (PMID 39988665, 2025). "In contrast, in melanoma and head and neck SCCs, TLR3 activation is associated with good prognosis and tumor regression, likely because of TLR3 activation of apoptosis-inducing mechanisms." (PMID 39348939, 2024). "Poly(I:C)-mediated immune activation depends on Toll-like receptor 3 (TLR3), and melanoma differentiation-associated gene-5 (MDA-5), for driving cell-mediated immunity and type I interferon response." (PMID 36556292, 2022). "TLR3 overexpression is often associated with a good prognosis or good response to TLR3 agonists in patients affected by hepatocellular carcinoma, melanoma, lung adenocarcinoma, and renal cancer." (PMID 33147700, 2020). "A haplotype for the TLR3 gene (C-G-G-T-A-G-G) was associated with a decreased susceptibility to melanoma (OR 0.57, 95%CI 0.35–0.95) compared to the most frequent haplotype (C-G-A-C-C-C-A)." (PMID 21931695, 2011). "Another group found an association between constitutive toll-like receptor 3 (TLR-3) activation and constitutive Wnt5A expression in melanoma cell lines." (PMID 24281103, 2010). "Hence, in this study, we first used Aza to stimulate B16-F10 melanoma cells to express TLR3 on the cell surface and further linked it with SZU-106, a TLR7 agonist, to the cell surface with a pegylated linker." (PMID 35805071, 2022). "PCR array analysis revealed that human mast cells up-regulated several anti-viral genes, including melanoma differentiation-associated gene 5, retinoic acid-inducible gene-I, and Toll-like receptor 3, together with type I interferons and chemokines, upon VSV infection." (PMID 25550087, 2015). "The association between TLR3 and caspase-3 expression, as a proof of the activation of apoptosis cascade in lung cancer, is supported by evidences in other cellular models of different cancer types, including breast, melanoma, head and neck, prostate, renal carcinoma, colon, and cervical cancers." (PMID 32093313, 2020). "Other immune cells have been shown to interact with melanoma exosomes; RNA from either melanoma cells or Lewis lung carcinoma cell-derived exosomes are taken up by lung epithelial cells and result in activation of Toll-like receptor-3 (TLR3) in these cells and causes the infiltration of neutrophils." (PMID 27941674, 2016). "Recent reports suggest that TLR3 signaling stimulates tumor growth in melanomas and head and neck squamous cell cancers by mediating cancer cell migration." (PMID 40029556, 2025). "Lung epithelial cells are critical for initiating neutrophil recruitment and lung metastatic niche formation by sensing tumor exosomal RNAs via TLR3 in melanoma." (PMID 40564191, 2025). "Studies have demonstrated that snRNAs derived from exosomes in lung cancer or melanoma can facilitate the establishment of a premetastatic microenvironment by activating Toll-like receptor 3 (TLR3) and promoting the release of cytokines." (PMID 40231207, 2025). "For example, it has been shown that FMX functionalized with a Toll-like receptor 3 agonist enhanced melanoma tumor control." (PMID 38251153, 2024). "TLR3 stimulation with dsRNA is considered to directly promote tumor-cell apoptosis in many types of cancer, such as breast, melanoma, prostate, cervical, colon, and hepatocellular carcinoma." (PMID 37005579, 2023). "Ferumoxytol was also combined with a toll-like receptor 3 (TLR3) agonist to activate macrophages for halting melanoma growth." (PMID 34976214, 2022). "Administration of a TLR3 agonist, polyI:C, induces therapeutic activity in melanoma, colorectal cancer and breast cancer in preclinical models." (PMID 36230990, 2022).